TP53TG3D (TP53 target 3D)
Gene: Protein-coding gene on chromosome 16 (32,253,286 to 32,255,928, forward strand). Ensembl gene ENSG00000205456.
Subcellular location: Cytoplasm; Nucleus
Subcellular location (Human Protein Atlas): Centriolar satellite
Gene Ontology:
Cellular component: cytoplasm; nucleus
Genetic constraint (gnomAD): Loss-of-function variants: 0 observed, 2.78 expected, observed/expected ratio (o/e) 0, 90% interval 0 to 1.05. That is too few expected variants to judge how well the gene tolerates losing a copy. Missense variants: 1 observed, 36.43 expected, observed/expected ratio (o/e) 0.0275, 90% interval 0.009 to 0.13. Synonymous variants: 1 observed, 14.08 expected, observed/expected ratio (o/e) 0.071, 90% interval 0.024 to 0.34.
Homologues: Paralogues in human: TP53TG3 (100% identical), TP53TG3B (100% identical), TP53TG3C (100% identical), TP53TG3E (100% identical), TP53TG3F (100% identical).